PTOV1 (PTOV1 extended AT-hook containing adaptor protein)
Diseases named in the same sentence as PTOV1 in open-access papers (continued):
Sharing a sentence is not in itself a finding about the gene and the disease.
tumor (10 papers, 2014 to 2019). "To study the long-term effect of the silencing of PIN1 and PTOV1 on cell proliferative potential, we performed colonogenic assay which is associated with tumor formation in vivo." (PMID 31083670, 2019). "PTOV1 is overexpressed and significantly associated to a high grade of malignancy, increased proliferation, and unfavorable prognosis in a number of other neoplasias." (PMID 28938627, 2017). "In human PC cell lines, the downregulation of PTOV1 induced an upregulation of the endogenous HEY1 and HES1 genes, and reciprocally, the ectopic expression of PTOV1 in PC cells and HaCaT keratinocytes, where Notch acts as tumor suppressor, caused the inhibition of expression of HEY1 and HES1 genes." (PMID 28029646, 2017). "The oncogenic protein PTOV1 is associated to bad prognosis in several tumor types." (PMID 28938627, 2017). "Additionally, PTOV1 was reported to be associated with tumor development and progression." (PMID 24947166, 2014). "Lastly, we verified inhibiting PTOV1 sensitizing NSCLC to chemotherapy in vivo using H460 xenograft tumor model." (PMID 31387622, 2019). "Upon analyzing data of multiple microarrays from the NCBI/GEO and TCGA database, we found that PTOV1 was consistently upregulated in tumor tissues of NSCLC comparing to the normal control." (PMID 31387622, 2019). "Surprisingly and consistently, compared to the normal lung tissues, PTOV1 mRNA was obviously upregulated in NSCLC tumor tissues in all analyzed files." (PMID 31387622, 2019). "Tumor sphere formation assays showed that depleting PTOV1 significantly reduced the size and number of spheres than that formed by the vector cells." (PMID 31387622, 2019). "In further experiment, the expression of PTOV1 was analyzed during the differentiation process induced by serum exposure of tumor spheroids." (PMID 31387622, 2019). "Depleting PTOV1 only slightly inhibited tumor growth as indicated by the tumor volume and weight when receiving no treatment." (PMID 31387622, 2019). "Depleting PTOV1 impaired tumor sphere formation, reduced CD133+ cell population and decreased the expression of pluripotency factors of NSCLC cells." (PMID 31387622, 2019). "Many questions remain to be solved to understand what is the biological role of PTOV1 in normal tissues, or how does the protein promote tumor progression." (PMID 28029646, 2017). "Significantly, the associated overexpression of the protein in more aggressive tumors with poor prognosis provides support for a role of PTOV1 in favoring CSCs self-renewal and tumor progression." (PMID 28029646, 2017). "Consistent with the mRNA analysis, PTOV1 protein levels were also increased in LSCC tissues compared with the surrounding non-tumor regions." (PMID 26992242, 2016). "Aberrant PTOV1 expression increased the number of cells that entered into the S phase of the cell cycle and increased tumor cell proliferation capacity; thus contributing to their biological behavior." (PMID 26992242, 2016). "Consistently, real-time PCR analysis revealed that PTOV1 mRNA was upregulated in tumor samples, further confirming that PTOV1 is overexpressed in NPC tissues." (PMID 26305455, 2015). "Accumulating evidence has revealed that PTOV1 plays a vital role in carcinogenesis and tumor progression." (PMID 26305455, 2015). "In xenograft experiments, tumor cells overexpressing PTOV1 showed an increased growth rate and tumorigenic capacity." (PMID 24947166, 2014). "These pro-oncogenic functions of PTOV1 were also observed in HaCaT keratinocytes, in which Notch behaves as a tumor suppressor." (PMID 24684754, 2014). "Tumor tissues were analyzed at single-cell level by immunohistochemistry for the expression of PTOV1, HEY1 and HES1 proteins on serial sections from 20 primary tumors (n = 10 with Gleason < 7 and n = 10 with Gleason > 7) and 16 lymph node metastases." (PMID 24684754, 2014). "However, when treated with docetaxel, depleting PTOV1 significantly reduced tumor growth compared with the vector group." (PMID 31387622, 2019).
tumor (continued). "In line with this possibility, our findings suggest that aggressive tumor cells with increased expression of PTOV1, ALDH1A1, and CCNG2 might correspond to potential CSCs with great capacity to metastasize and higher resistance to docetaxel." (PMID 28938627, 2017). "Therefore, we assumed that PTOV1 is a positive regulator of LSCC tumor cell proliferation and progression that acts via the transcription factor c-Jun and its downstream genes." (PMID 26992242, 2016). "Indeed, in other models, PTOV1 was reported regulating stemness of tumor cells." (PMID 31387622, 2019). "Thus, the nuclear presence of PTOV1 might be critical for proliferation and tumor progression, suggesting that its transcription regulating abilities are relevant functions." (PMID 28029646, 2017). "The contrasting activities of PTOV1 and HES1 and HEY1 were also tested in HaCaT transformed skin keratinocytes, a cellular model in which Notch has known tumor suppressor functions." (PMID 24684754, 2014). "What’s more, tumor sphere formation assay showed siDKK1 increased tumor sphere formation ability of PTOV1-Sg2 cells, which proved that inhibiting DKK1 restored stemness of PTOV1-depleted cells." (PMID 31387622, 2019). "In turn, increased levels of PTOV1 and c-Jun induced SNAI1 transcription, promoted an epithelial-mesenchymal-transition (EMT) and a significant increase of cell invasiveness in vitro and tumor growth and metastasis in vivo." (PMID 28029646, 2017). "PTOV1 mRNA was expressed at significantly higher levels in the LSCC tissue samples than in the non-cancerous tissues, with at least 10-fold higher levels observed in the tumor tissues." (PMID 26992242, 2016). "PTOV1 was mainly localized in the tumor cell cytoplasm, with strong nuclei staining occasionally observed; little or no expression of PTOV1 was observed in the normal epithelial cells." (PMID 26992242, 2016). "Among 123 samples, high levels of PTOV1 expression were detected in 68 samples (55.3%) and weak or no staining was observed in 55 tumor samples (44.7%)." (PMID 26305455, 2015). "Knockdown of PTOV1 in PC-3 cells led to a strong upregulation of HES1 and HEY1 both in vitro and in cells implanted in SCID-beige mice, accompanied with a significant delay in tumor growth and metastatic spread." (PMID 24684754, 2014). "Hence, we draw a conclusion that PTOV1 is crucial in drug resistance but might not in tumor initiation in NSCLC." (PMID 31387622, 2019).
adenocarcinoma (1 paper, 2014). A common cancer characterized by the presence of malignant glandular cells. "Epithelial cells from BPZ showed undetectable or faint staining for PTOV1, while a gradual increase in staining intensity was observed from HGPIN lesions to adenocarcinoma lesions, which generally showed a strong staining." (PMID 24684754, 2014).
PTOV1 also shares sentences with these, for which no sentence is quoted: intraepithelial neoplasia (2 papers); metastatic prostate carcinoma (2); prostate intraepithelial neoplasia (2); urothelial carcinoma (2); Atrophy (1); cervical cancer (1); endometriosis (1); esophageal cancer (1); hepatocellular carcinoma (1); lung squamous cell carcinoma (1).